MIR576 (microRNA 576)
Synonyms: hsa-mir-576; MIRN576
Gene: MicroRNA gene on chromosome 4 (109,488,698 to 109,488,795, forward strand). Ensembl gene ENSG00000207988.
Gene Ontology:
Biological process: miRNA-mediated post-transcriptional gene silencing
Cellular component: RISC complex